SMO (smoothened, frizzled class receptor)
Diseases named in the same sentence as SMO in open-access papers (continued):
Sharing a sentence is not in itself a finding about the gene and the disease.
tumor (continued). "Treatment of SCLC PDX xenografts with the SMO antagonist, sonidegib, alone mildly inhibited tumor growth." (PMID 36010600, 2022). "Shh-SMO pathway inhibition with a Smoothened antagonist was shown to impair tumour growth, switch the CAF balance from myCAF to iCAF, and alter the immune TME in murine PDAC." (PMID 36358721, 2022). "Further investigations are needed to evaluate the possible impact of SMO inhibitors on the systemic immune response, as well as the potential effect of such drugs in the treatment of other neoplasms." (PMID 35775005, 2022). "Alternatively, activating mutations in SMO are often found in spontaneous BCC, and rarely in other tumor types." (PMID 36091167, 2022). "Inhibitors of GLI‐mediated transcription, such as GANT58 and GANT61, were first designed to overcome tumor resistance to SMO inhibitors." (PMID 36226253, 2022). "The tumor growth in this autocrine manner can be effectively suppressed by Hh neutralizing antibodies or SMO antagonists." (PMID 35163655, 2022). "HH signaling supports glioma tumor growth in animal models by inducing SMO‐expressing gliomasphere formation." (PMID 36226253, 2022). "More recently, pharmacological inhibition of SMO (via LDE225) in tumor-bearing mice was shown to increase the recruitment of immunosuppressive macrophages and decrease the relative proportion of cytotoxic T cells." (PMID 35867772, 2022). "In human HCC tumors, expression of SMO positively correlated with tumor size, while an inverse relationship was reported for PTCH1, suggesting overaction of Hh signaling as a result of SMO derepression." (PMID 34572373, 2021). "On the other hand, patient P15 presents in each tumor different variants, of which a variant in PTCH1 and another in SMO are considered as responsible for BCC in the first and second tumors, respectively." (PMID 34284772, 2021). "Results demonstrated that with the depletion of SMO, tumor growth rate was slowed down and the final tumor weight was then reduced compared with control groups." (PMID 33771969, 2021). "Blockage of PTCH1 and SMO activity with vismodegib-inhibited tumor growth in both HBx-transgenic mice and HBx-positive human HCC xenograft models." (PMID 33440657, 2021). "Nonetheless, cilia have also been demonstrated to exert tumor-suppressive activity for oncogenic HH signaling initiated downstream of SMO." (PMID 34638386, 2021). "Thereafter, we comprehensively evaluated the associations between tumor location (embryological origin), pathological diagnosis (histological type), and driver mutations including AKT1, KLF4, SMO, POLR2A, and NF2 mutations." (PMID 33772057, 2021). "Here, it is noteworthy that SMO inhibitors alone rarely eliminate all tumor cells, which allows residual tumor cells to persist and regrow." (PMID 34439381, 2021). "In MB-prone mice with a SMO mutation, the TME contains tumor cell types that exist across a spectrum of differentiation states and tumor-derived cells that express makers for astrocytic and oligodendrocytic precursors." (PMID 34436033, 2021). "This is important considering that the Shh-type MB patients treated with Shh/SMO antagonists have rapid tumor recurrence." (PMID 34395258, 2021). "Vismodegib is able to bind the TMD of SMO and to induce tumor regression in a Ptch+/- derived MB allograft mouse model." (PMID 34164380, 2021). "Targeting SMO and the GLIs have been demonstrated to be a valuable strategy to block the HH signaling pathway activity and suppress the tumor progression." (PMID 34956733, 2021). "Taken together, these results establish compound 4s as a novel SMO antagonist that curtails HH-dependent tumour growth, both in vitro and in vivo." (PMID 34445078, 2021). "In 33 tumor cell lines, SMO gene expression was highest among all Hh members, and its expression was significantly and positively correlated with GLI2 transcript levels." (PMID 34572373, 2021).
tumor (continued). "Data from IHC assay verified similar results that SMO deficiency hindered tumor growth, as the positivity of two proliferative markers (Ki-67 and PCNA) was markedly reduced in tumors with silenced SMO." (PMID 33771969, 2021). "We provide evidence that inhibition of CSNK1D interferes with oncogenic HH signaling in both SMO inhibitor-sensitive and -resistant tumor settings." (PMID 34439381, 2021). "On the other hand, a recent study has shown that deletion of SMO in fibroblasts led to increased proliferation of tumor cells and proteasomal degradation of the tumor suppressor PTEN and was associated with poorer survival in PDAC patients." (PMID 34944807, 2021). "This includes overexpression of HH ligand in tumor and tumor microenvironment (TME), loss of function mutation in PTCH1 and SUFU, GLI2 amplifications, and gain of function mutation in SMO." (PMID 34831357, 2021). "Targeting the Sonic hedgehog (SHH)–Smoothened (SMO) signaling axis increases cancer cell proliferation, owing to inhibition of the tumor-restraining phenotypes of myCAF by SHH-SMO." (PMID 35008832, 2021). "We identified compound 4s as a SMO antagonist that induced apoptosis and reduced the expression of several HH signalling pathway target genes involved in tumour growth." (PMID 34445078, 2021). "For example, in two Hh pathway-dependent mouse basal cell carcinoma models, cilia deletion was able to inhibit tumor growth induced by an activated form of SMO, but also promote tumor growth induced by activated GLI2." (PMID 33339422, 2020). "In 90% of these tumours, mutations in the MAPK pathway are found, with BRAF V600E being the most common mutation, whilst outside the MAPK pathway SMO mutation is the most frequently referenced." (PMID 32388513, 2020). "The upregulation of downstream effectors in the HH signaling cascade such as GLI1 has been suggested as a possible mechanism to explain tumor resistance to the SMO inhibitors, as is the case with vismodegib." (PMID 32913560, 2020). "SMO si-RNA-transfected gallbladder cancer cells underwent a decrease in tumor volume according to a xenograft study." (PMID 31979397, 2020). "Analysis of the association of the genotypes found for CpG-SNP rs75827493 (T> G) of the SMO gene with the variables of: gender, age, anatomical localization of the neoplasia and histopathological types." (PMID 31983159, 2020). "In TNBC, some researchers found a correlation between SMO expression and histological grade or tumor stage." (PMID 31979397, 2020). "Overexpression of SMO induces the expression of c-Myc, which plays a significant role in hepatocarcinogenesis and SMO overexpression is correlated with tumor sizes." (PMID 32962123, 2020). "Consistent with EAC viability being HH ligand-dependent, SMO shRNA reduced tumor cell viability and ability of all four EAC cell lines to grow in a colony formation assay." (PMID 32913560, 2020). "The same experimental study designed to knock out SMO in mice models revealed reduction in tumor size and metastasis." (PMID 33489917, 2020). "Disrupting the HH pathway by pharmacological SMO inhibition slowed tumor growth in a subcutaneous tumor model, and slightly prolonged survival when combined with chemotherapy in a tumor-bearing KPC mice." (PMID 33198201, 2020). "Experimental work on genetically engineered mice models exhibits that in knock-out PTCH gene mice model organism, increased expression of SMO was observed with increased tumor size." (PMID 33489917, 2020). "Since SMO‐mediated Hedgehog signalling plays critical roles in tumour occurrence and progression, this study aimed to investigate the regulatory effect of SP1/miR‐326 axis on Hedgehog signalling." (PMID 32743904, 2020). "As the results shown that circSMO742 and SMO protein had higher protein expression levels while miR-338-3p had lower expression level in tumor cells, compared with normal cells." (PMID 31895689, 2019).
tumor (continued). "Based on the inverse correlation between the expression of Sufu and Gli1, specifically after vismodegib treatment, we propose that vismodegib sensitizes tumor cells to SUFU-mediated inhibition by reducing stimulation through SMO and SMOM2." (PMID 31863004, 2019). "In these GC lines, Hh inhibition with SMO shRNA or small-molecule inhibitors significantly suppressed spheroid formation and tumor growth." (PMID 31775795, 2019). "Recently, inhibition of the HH pathway in BCC patients with the SMO Inhibitors vismodegib or sonidegib led to increased levels of MHC-I expression on tumor cells together with an increase of CD4 and CD8 positive T-cells in the peri- and intra-tumoral regions." (PMID 31878932, 2019). "Consistently, inhibition of BRD4 led to a reduction of GLI activity and tumor growth in both SMO-dependent and -independent cancer models." (PMID 30991683, 2019). "In a TNBC cohort, increased SHH and SMO expression was associated with high histological grades, and SMO and GLI1 correlated with high tumor stages." (PMID 31027259, 2019). "Initial IDHWT tumours also showed predicted pathogenic variation in NOTCH (11%) and SHH (13%) pathways including PTCH1 (PATCHED-1) and SMO (Smoothened)." (PMID 32082376, 2019). "In particular, SMO inhibitors have been shown to effectively suppress this subgroup of tumours in clinical trials." (PMID 30100614, 2018). "This approach led to an overestimation of the range of tumour types that appear to respond to SMO inhibitors." (PMID 30068568, 2018). "By contrast, the other SMO inhibitors only exhibited inhibitory effects on tumour cell growth when used at concentrations several hundredfold higher than those required to achieve target inhibition." (PMID 30068568, 2018). "A recent study found that Arl13b directly binds to and stabilizes SMO and that higher levels of Arl13b prevent the degradation of SMO and accelerate tumor growth." (PMID 30410731, 2018). "Despite an impressive initial response in some metastatic BCC patients, durable tumor growth suppression by SMO antagonists has been elusive and few treatment options that are available to patients after progression." (PMID 29348431, 2018). "In the case of SMO inhibitors, the primary mechanism appeared to be inhibition of tumour cell proliferation, leading to abortive differentiation and ultimately cell death." (PMID 30068568, 2018). "The MAPK/ERK (mitogen-activated protein kinase/extracellular signal-regulated kinase) pathway (also known as RAS-RAF-MEK-ERK) has been identified as a way to evade SMO inhibition and drive tumor evolution in HH-dependent tumors." (PMID 30558232, 2018). "The first published report, investigating the efficacy of the SMO inhibitor cyclopamine as an anticancer agent, used cultured tumour cells from mice and humans as well as allograft tumours established from mouse tumour cell lines." (PMID 30068568, 2018). "In BCC, a number of Hh pathway-dependent mechanisms have been identified which contribute to tumour recurrence in response to treatment with SMO inhibitors." (PMID 30379908, 2018). "The authors concluded that the previously reported effects of SMO inhibitors on growth and HH pathway activity in tumour cells were a consequence of off-target effects resulting from the use of the inhibitors at high, non-physiological concentrations." (PMID 30068568, 2018). "Unlike BCC and MB, no activating mutations in HH pathway genes have been reported in the other tumours proposed to be treated with SMO inhibitors." (PMID 30068568, 2018). "Inhibition of SMO hinders downstream activation of GLI transcription factors, leading to repression of target genes associated with tumor growth and progression." (PMID 30558232, 2018). "Attempts had already been made to investigate the potential of statins alone, or in combination with the SMO inhibitor cyclopamine, for the treatment of MB and other tumours thought to be dependent on HH pathway activity." (PMID 30068568, 2018).
tumor (continued). "In our previous studies, we found that SHH signaling pathway contribute to mediate the tumor-like behavior of FLSs depending on SMO." (PMID 30568656, 2018). "Although SMO inhibitors have shown promising antitumor effects against a variety of tumor types in preclinical models, several studies have reported disease progression within several months due to the acquisition of resistance." (PMID 30558232, 2018). "SEN450 is a potent benzimidazole derivative that was shown to inhibit SMO and to reduce tumor volume in a glioblastoma multiforme xenograft model." (PMID 30558232, 2018). "In this cohort, Giannikopoulus and colleagues demonstrated the presence of SMO gene amplification in tumor biopsies taken at occurrence of resistance to EGFR-TKIs in 12,5% patients concomitantly with MET gene amplification." (PMID 28416737, 2017). "It is a derivate of cyclopamine and potently inhibits SMO, thus efficiently reducing Hh pathway activation and in turn decreasing tumor growth in in vivo models." (PMID 28948003, 2017). "Our data suggest a partially SMO-independent GLI transcriptional activity in the PhKh1 cells which has been described in other tumor entities." (PMID 29371980, 2017). "SMO and PTCH mutations are found in sporadic BCC and medulloblastomas in their early stage of tumor growth." (PMID 29163356, 2017). "Treatment with AZD8542 has been able to decrease the expression of SMO and inhibit tumor growth in human pancreatic stellate cells (HPSCs)." (PMID 28948003, 2017). "We first monitored the effect of DYRK1B inhibition on tumor-initiating spheroid formation of GLI1-dependent yet SMO-inhibitor resistant PANC-1 cells in 3D cultures." (PMID 26784250, 2016). "GLI2 expression and osteolytic ability of metastatic tumor can be inhibited by abolishing TGFβ signaling, indicating SMO-downstream regulation of GLI2 via TGFβ cascade." (PMID 26343727, 2015). "Together, these data show that ERMS and ARMS cell lines show tumor-intrinsic HH signaling activity as estimated by modulation of GLI1 expression after treatment with SMO – antagonists." (PMID 26106586, 2015). "Tumor growth was significantly attenuated in several tumor models with constitutive Hh pathway activation, even with resistance to SMO inhibitors." (PMID 26053182, 2015). "Again, this tumour growth is impeded in response to the inhibition of the Hh pathway with either cyclopamine, 5E1 or the small molecule SMO antagonist, SANT-1." (PMID 26270676, 2015). "Ten variants were identified from eight genes in both the tumor and normal groups (APC, EGFR, FGFR3, KDR, MET, PDGFRA, RET and SMO)." (PMID 25404506, 2014). "These loci are respectively known to harbour tumour-associated genes, including TIF, BRAF, MLL3, SMO, and MET." (PMID 24289252, 2013). "Whereas Kifa3 is required for activated SMO-mediated tumor formation, deletion of Kifa3 catalyzes Gli2-mediated carcinogenesis." (PMID 23303278, 2013). "Drug development efforts aimed at inhibiting the HH pathway in tumour cells have hitherto been focused on the GPCR-like receptor SMO." (PMID 24311597, 2013). "There is an unmet clinical need for the development of SHHpathway-independent targeted therapies for SHH subgroup tumours, particularly inview of the predicted acquired or intrinsic resistance to current SMO inhibitors." (PMID 24252690, 2013). "Although MS-0022 primarily interferes with Hh signaling at the level of SMO, it also has a downstream inhibitory effect and leads to a stronger reduction of growth in several tumor cell lines when compared to related SMO antagonists." (PMID 21698280, 2011). "Several recent papers have demonstrated that anti-tumor effect by SMO inhibitors are mostly due to their effect on stromal cells." (PMID 20067614, 2010).
tumor (continued). "This resistance could be attributed to the critical role of the Hh pathway in BCC pathogenesis despite its low affinity for SMO transducers and limited tumor development." (PMID 40522768, 2025). "Finally, we demonstrate that activation of the Gαs-coupled adenosine 2B receptor counteracts oncogenic SMO, reducing Hedgehog signaling and tumor formation and offering a potential therapeutic strategy for BCC." (PMID 40060632, 2025). "Our study found that SH downregulated the protein and mRNA expression of SHh, PTC, SMO, Gli1, and Gli2 in the Hedgehog pathway, suggesting that SH might inhibit tumor progression via suppressing the Hedgehog pathway activation." (PMID 41444284, 2025). "The interpretation is consistent with current evidence showing that while some SMO mutations confer resistance to inhibitors like sonidegib, not all mutations do, and tumor heterogeneity plays a crucial role in therapeutic outcomes." (PMID 41515948, 2025). "The association between higher SMO expression and increased mitotic activity in BCC is notable, as it may correlate with more aggressive tumor variants." (PMID 40542075, 2025). "Furthermore, simultaneous inhibition of both DNMT1 and SMO acts synergistically to inhibit tumor growth in in vitro and in vivo models of SHH-MB." (PMID 39107797, 2024). "Interestingly, the LY6D+ SMO inhibitor-resistant tumor cells, extensively cover the morphological and transcriptional cell states of basal to squamous cell carcinoma transition." (PMID 39558960, 2024). "Furthermore, our data indicate that continuous combination therapy of DNMT1 and SMO inhibitors acts synergistically to inhibit tumor growth." (PMID 39107797, 2024). "Studies indicate that the inhibition of GLI may be more effective than SMO in blocking tumor growth in several cancer models." (PMID 38999049, 2024). "The exact cause of this phenomenon remains uncertain; however, aberrations in the SMO gene can result in anomalous stimulation of the Sonic Hedgehog (SHH) pathway, potentially causing heightened cellular proliferation and the development of tumours." (PMID 38672677, 2024). "Moreover, the mechanisms underlying BCC regression remain incompletely understood, with residual tumor cells often persisting despite SMO inhibition, leading to BCC recurrence post-treatment discontinuation." (PMID 39086988, 2024). "Third, inhibition of DNMT1 blocked SHH pathway output as supported by a previous study, and pathway inhibition as well as anti-tumor activity were also seen in the presence of genetic alterations within the SHH pathway previously shown to render tumors resistant to SMO inhibition." (PMID 39107797, 2024). "Additionally, by employing chemogenetic CRISPR-Cas9 screens, we discovered that SMO inhibition acts synergistically with DNMT1 inhibition in suppressing tumor proliferation in murine as well as PDOX (patient-derived xenografts organoids) SHH-MB models." (PMID 39107797, 2024). "Similarly, ciliary ablation in basal cell carcinoma (BCC)‐like tumours, induced by an activated form of SMO, inhibited the growth of carcinoma, conversely, in tumours induced by activated GLI2, carcinogenesis was accelerated." (PMID 39234399, 2024). "It is thought that cilia deletion could activate SMO to inhibit tumor growth, while promoting carcinogenesis was induced by activated Gli2." (PMID 37737843, 2023). "Interestingly, in all tumour samples, with G4 being the only exception, there was an increase in SMO, and it is only expressed in G4." (PMID 37240278, 2023).